PGPEP1 (pyroglutamyl-peptidase I)
Description:
Removes 5-oxoproline from various penultimate amino acid residues except L-proline.
Synonyms: PAP-I; PGP-I; PGPI; Pcp; PGP; PGI
Tractability: PROTAC: ubiquitination databases record sites on it.
Target class: Enzyme; Hydrolase
Gene: Protein-coding gene on chromosome 19 (18,340,587 to 18,369,950, forward strand). Ensembl gene ENSG00000130517.
Subcellular location: Cytoplasm
Subcellular location (Human Protein Atlas): Golgi apparatus
Gene Ontology:
Molecular function: peptidase activity; pyroglutamyl-peptidase activity
Biological process: protein catabolic process; proteolysis
Cellular component: cytoplasm; cytosol
Genetic constraint (gnomAD): Loss-of-function variants: 16 observed, 19.42 expected, observed/expected ratio (o/e) 0.82, 90% interval 0.56 to 1.25. The upper end of that interval is the gene's LOEUF score, 1.25, which puts it in group 5 of 6, group 1 being the genes least tolerant of losing a copy. Missense variants: 218 observed, 250.04 expected, observed/expected ratio (o/e) 0.87, 90% interval 0.78 to 0.98. Synonymous variants: 108 observed, 104.67 expected, observed/expected ratio (o/e) 1.03, 90% interval 0.88 to 1.21.
Homologues: Orthologues: chimpanzee PGPEP1 (100% identical), dog PGPEP1 (98% identical), guinea pig PGPEP1 (96% identical), mouse Pgpep1 (95% identical), rat Mk1 (94% identical), pig PGPEP1 (93% identical), macaque PGPEP1 (89% identical), rabbit PGPEP1 (81% identical), tropical clawed frog pgpep1 (74% identical), zebrafish pgpep1 (68% identical), Caenorhabditis elegans M04C9.3 (32% identical), Drosophila melanogaster CG32147 (31% identical), and 7 more. Paralogues in human: PGPEP1L (27% identical).
Diseases named in the same sentence as PGPEP1 in open-access papers:
PGPEP1 is named in the same sentence as 3 diseases in open-access papers, as found by Europe PMC text mining. Sharing a sentence is not in itself a finding about the gene and the disease. The quoted sentences say what the papers report.
Tumor (2 papers, 2021 to 2023). "Tumor showed upregulation of HOOK3 chr8:42883441A > I, PGPEP1 chr19:18476416A > I, and NDUFV3 chr21:44329452A > I, as compared with normal tissue." (PMID 36999050, 2023). "ANKRD36BP1 (dist = 3,795), TBX19 (dist = 29815) chr1:168220463A > I (p < 0.001), HOOK3 chr8:42883441A > I (p = 0.0011), PGPEP1 chr19:18476416A > I (p < 0.001), and NDUFV3 chr21:44329452A > I (p = 0.038) were significantly different between tumor and normal tissues." (PMID 36999050, 2023).
PGPEP1 also shares sentences with these, for which no sentence is quoted: esophageal carcinomas (1 paper); fibromyalgia (1).